IDO1 (indoleamine 2,3-dioxygenase 1)
Diseases named in the same sentence as IDO1 in open-access papers (continued):
Sharing a sentence is not in itself a finding about the gene and the disease.
liver fibrosis (19 papers, 2017 to 2025). "Conversely, ginsenoside-Rg1, isolated from ginseng, protects against IDO1 overexpression-dependent mechanisms implicated in the progression of hepatic fibrosis in animal models." (PMID 39120289, 2024). "Our results indicated IDO1-deficient fibrotic mice exhibited milder liver fibrosis than WT fibrotic mice, whereas overexpression of IDO1 led to worsening liver fibrosis." (PMID 33414436, 2021). "IDO1 deficiency prevents the progression of hepatic fibrosis induced by CCl4, the underlying mechanism of which is related to a decrease in Th17 cells mediated by a compensatory increase in TDO." (PMID 28465467, 2017). "In conclusion, we demonstrate that serum IDO1 is a potential hallmark of liver lesions and the degree of liver fibrosis in patients and in an animal model." (PMID 28465467, 2017). "Further support to this notion comes from present work, the dramatically upregulated expression of hepatic IDO1 after BDL was identified in WT mice, and its role during the development of liver fibrosis was repeated validations by experiments applying IDO1-deficient and IDO1-overexpression mice." (PMID 33414436, 2021). "However, a recent study demonstrated that IDO1 deficiency aggravated liver fibrosis in a CCl4-induced liver injury model." (PMID 28465467, 2017). "Above results corroborate our previous hypothesis suggest that the observed changes in immune cells recruitment of DCs and T-cell presented a transform in hepatic inflammatory microenvironment might cause by the different expression level of IDO1 during BDL-induced liver fibrosis." (PMID 33414436, 2021). "However, whether IDO1 is involved in DCs activation and maturation during liver fibrosis and the underlying immunoregulatory mechanisms are still poorly understood." (PMID 33414436, 2021). "Thus, the level of serum IDO1 might be regarded as a potential hallmark of liver lesions and the degree of liver fibrosis." (PMID 28465467, 2017). "Further analysis indicated that IDO1-mediated kynurenine increased the activation of hepatic stellate cells, thus promoting the progression of liver fibrosis." (PMID 39940736, 2025). "Treatment with IDO1 inhibitors significantly alleviated liver fibrosis, suggesting that kynurenine metabolism plays a critical role in chronic liver injury and fibrosis." (PMID 39940736, 2025). "A parallel mechanism has been identified in hepatic fibrosis pathogenesis, where IDO1 establishes a pro-fibrogenic positive feedback loop between hepatic stellate cells (HSCs) and Kupffer cells through upregulation of TGF-β1/Smad3 signaling." (PMID 40370742, 2025). "Corilagin mediates the repolarization of M2 macrophage to M1 macrophage by inhibiting the expression of Indoleamine 2,3-Dioxygenase 1 (IDO1), thereby improving CCl4-induced liver fibrosis." (PMID 41154556, 2025). "IDO1 has been identified as a significant factor in the development of hepatic fibrosis and a potential therapeutic target." (PMID 39120289, 2024). "Its administration significantly reduces hepatic IDO1 expression levels, resulting in decreased hepatocyte apoptosis rates in hepatic fibrosis mouse models." (PMID 39120289, 2024). "As such, IDO-1 inhibitors serve as a promising therapeutic target, having also demonstrated value in ameliorating liver fibrosis and targeting cancer immune escape." (PMID 39774873, 2024). "It has been shown in a murine model of liver fibrosis with CCL4 that hepatic Tdo2 is upregulated in Ido1−/− mice." (PMID 35563591, 2022). "By contrast, overexpression of IDO1 significantly aggravated liver fibrosis, accompanied by a dramatically reduced percentage of CD11c+MHCII+, CD11c+CD40+ cells and CD3+, CD3+CD4+ T cells in hepatic NPCs of fibrotic livers." (PMID 33414436, 2021). "Our data demonstrate that IDO1 affects the process of immune cells recruitment via inhibiting DCs maturation and subsequent T cells proliferation, resulting in the promotion of hepatic fibrosis." (PMID 33414436, 2021).
liver fibrosis (continued). "Collectively, these results suggest that IDO1 appeared crucial for trafficking of these immune cells during liver fibrosis." (PMID 33414436, 2021). "To investigate the pathological role of IDO1 in liver fibrosis, we found the classical animal model of liver fibrosis by bile duct ligation." (PMID 33414436, 2021). "The primary concern of subsequent study was to observe the difference between WT and IDO1−/− mice in response to BDL-induced liver fibrosis." (PMID 33414436, 2021). "Ginseng Rg1 also significantly reduced the aspartate transaminase (AST) and ALT expression levels in serum in CCl4-induced liver fibrosis in mice (wild-type and those overexpressing IDO1 by in vivo AAV9 vector) and HSC-T6 cells." (PMID 34869457, 2021). "In this study, we investigated the role of IDO1 in the development of hepatic fibrosis and cirrhosis." (PMID 28465467, 2017). "To evaluate the changes in IDO1 levels in mice, we established a model of liver fibrosis induced by CCl4." (PMID 28465467, 2017). "For further investigation, we established a CCl4-induced liver fibrosis model in IDO1–/– mice and found that hepatic fibrosis was alleviated compared with the WT model mice." (PMID 28465467, 2017). "This evidence revealed the role of the blockade of Th17 cells in attenuating CCl4-induced liver fibrosis in IDO1–/– mice." (PMID 28465467, 2017). "Liver lesions were positively correlated with serum IDO1 levels in both the clinical subjects and hepatic fibrosis mice." (PMID 28465467, 2017). "For animals, carbon tetrachloride (CCl4) was used to establish liver fibrosis in wild-type and IDO1 knockout mice." (PMID 28465467, 2017). "IDO1 impairs the maturation of dendritic cells in wild-type (WT) mice and downregulates key regulators of cellular oxidative stress and inflammation, including nuclear factor E2-related factor 2, thus alleviating liver fibrosis." (PMID 39940736, 2025). "Consequently, IDO1−/− mice were challenged with BDL lasted for 3 weeks to evaluate the effects of IDO1 gene deletion to the outcome of liver fibrosis." (PMID 33414436, 2021). "This hypothesis was further validated in our research reported here, in IDO1-KO mice model, where exhibited markedly attenuated liver fibrosis, together with an elevated percentage of CD11c+MHCII+, CD11c+CD40+ cells in hepatic NPCs of fibrotic livers." (PMID 33414436, 2021). "The present work investigated the in vivo role of IDO1 in the pathogenesis of liver fibrosis through assessing the degree of liver fibrosis and maturation status of DCs induced by bile duct ligation (BDL) in wild-type (WT) mice, mice deficient in IDO1 and mice overexpression in IDO1." (PMID 33414436, 2021). "In addition, oral administration of Ginseng Rg1 ameliorated the deterioration of liver fibrosis induced by IDO1 overexpression and the more pronounced inhibition of DCs maturation mediated by IDO1 overexpression." (PMID 34869457, 2021). "Our results suggested that IDO1 accelerated the development of BDL-induced liver fibrosis by altered hepatic inflammatory cells recruitment including reduced hepatic CD11c+DC populations, made DCs presented an immature phenotype and reduced subsequent T cells proliferation." (PMID 33414436, 2021). "More importantly, overexpression of IDO1 diminished the anti-hepatic fibrosis effects of Danshensu." (PMID 34869457, 2021). "Consequently, we further made a comparison between the maturation status of hepatic CD11c+DCs in WT and IDO1−/− mice after induction of liver fibrosis by BDL." (PMID 33414436, 2021). "Notably, IDO1 overexpression inhibited hepatic, splenic CD11c+DCs maturation, mature DCs-mediated T-cell proliferation and worsened liver fibrosis, whereas above pathological phenomena were reversed in IDO1−/− mice." (PMID 33414436, 2021). "As expected, Sirius Red staining also proved that IDO1 overexpression led to worse liver fibrosis." (PMID 33414436, 2021).
liver fibrosis (continued). "Indoleamine 2,3-dioxygenase 1 (IDO1) is an intracellular rate-limiting enzyme in the metabolism of tryptophan along the kynurenine pathway, subsequently mediating the immune response; however, the role of IDO1 in liver fibrosis and cirrhosis is still unclear." (PMID 28465467, 2017). "Furthermore, these findings indicated that in mice with hepatic fibrosis, the level of serum IDO1 remained the same in the state of mild liver lesions but was increased under the condition of severe liver lesions." (PMID 28465467, 2017). "In the present study, we investigated the role of IDO1 in a clinical trial and in a carbon tetrachloride (CCl4)-induced hepatic fibrosis mouse model to obtain preclinical data for the treatment and/or chemoprevention of liver fibrosis (and even cirrhosis) by modulating IDO1 expression." (PMID 28465467, 2017). "As liver fibrosis is a dynamic process, IDO1 may play various roles at different stages of hepatic fibrosis." (PMID 28465467, 2017). "Notably, IDO1 knockout mice were protected from CCl4-induced liver fibrosis, as reflected by unchanged serum alanine transaminase and aspartate transaminase levels and lower collagen deposition, α-smooth muscle actin expression and apoptotic cell death rates." (PMID 28465467, 2017). "Moreover, under the condition of cirrhosis, this clinical study indicated positive correlations of the serum IDO1 level with liver lesions and the degree of hepatic fibrosis, despite the reduction in IDO1." (PMID 28465467, 2017). "Consequently, flow cytometry was also performed on splenic leukocytes to address whether splenic immune response contributes to the pro-fibrogenic role of IDO1 during BDL-induced liver fibrosis." (PMID 33414436, 2021). "Moreover, amelioration of immune response in the hepatic, splenic microenvironment by targeting IDO1 might be essential for the treatment effects on liver fibrosis." (PMID 33414436, 2021). "Thus, amelioration of immune responses in hepatic and splenic microenvironment by targeting IDO1 might be essential for the therapeutic effects on liver fibrosis." (PMID 33414436, 2021). "Thus, we hypothesize that under the condition of IDO1 deficiency, TDO increases in the liver to compensate, which can decrease the proliferation of Th17 cells in CCl4-induced liver fibrosis." (PMID 28465467, 2017). "Thus, our findings suggested that IDO1 may promote BDL-induced liver fibrosis." (PMID 33414436, 2021). "We then used wide-type (WT) and IDO knocked-out (IDO–/–) mice at the age of 6–8 weeks with matched body weights and investigated the role of IDO1 in regulating CCl4-induced liver fibrosis." (PMID 28465467, 2017). "In liver fibrosis and cirrhosis, the absence of IDO1 results in a compensatory increase in tryptophan 2,3-dioxygenase (TDO)." (PMID 40597301, 2025). "Moreover, research on Danshensu, a novel inhibitor of indoleamine 2,3-dioxygenase 1, has revealed that it inhibits JAK2-STAT3 signaling, resulting in reduced hepatic fibrosis." (PMID 40225863, 2025). "Moreover, corilagin, a gallotannin, mediating the reprogramming of alternatively activated macrophages to a pro-inflammatory phenotype by regulating the expression of Indoleamine 2,3-dioxygenase 1 (IDO1) in vitro, thereby alleviating liver fibrosis." (PMID 40977736, 2025). "Indoleamine 2,3-dioxygenase 1 (IDO1), an immunomodulatory enzyme, was highly expressed in choledochotomy (BDL)-induced mice, inhibiting DCs maturation and T cell proliferation from recruiting immune cells and promoting hepatic fibrosis." (PMID 37539053, 2023). "Interestingly, fibrosis reduction and inhibition of IDO1 expression and STAT3 activity were observed in vitro TGF-β1-induced hepatic stellate cell model and in vivo CCl4-induced rat hepatic fibrosis model after administration of Danshensu." (PMID 34869457, 2021).
liver fibrosis (continued). "Moreover, overexpression of liver‐specific IDO1 diminished numbers of splenic CD11c+MHCII+, CD11c+CD40+ cells and reduced CD3+, CD3+CD4+ T cells infiltration subsequently during BDL-induced hepatic fibrosis." (PMID 33414436, 2021). "Indoleamine 2,3-dioxygenase 1 (IDO1) can affect the infiltration of immune cells in many pathology processes of diseases, but its role in liver fibrosis has not been elucidated completely." (PMID 33414436, 2021). "Since both IDO1 and DCs play a crucial function in liver inflammation and immunity, we postulated IDO1 might play a critical role in modulating DCs in BDL-mediated liver fibrosis." (PMID 33414436, 2021). "Indeed, apart from the elevated expression of IDO1 in fibrotic livers, the frequency of hepatic CD11c+DCs reduced from ~39.1% in controls to ~16.2% in BDLs and undergo a transformation in mature phenotype in BDL-induced liver fibrosis." (PMID 33414436, 2021). "Additionally, knock out of IDO1 induced a distinct increase in the frequency of CD3+ T cells, and the ratio of CD4+/CD8+, whereas reduced the frequency of CD8+ T cells in hepatic NPCs under the condition of liver fibrosis." (PMID 33414436, 2021). "In addition, a more recent article observed that IDO2−/− mice and administration of 1-D-MT or Kyn also prevented severe liver cell damage and liver fibrosis, which suggested that the mechanism is not attributable to the contribution of IDO1." (PMID 34869457, 2021). "Although the critical role of IDO1 participated in the process of immune regulation during multiple courses of diseases had been demonstrated, the distinct function of IDO1 in the change of immune responses during liver fibrosis has not been studied." (PMID 33414436, 2021). "In conclusion, IDO1 was elevated significantly in fibrotic livers after BDL-operated and involved in the progression of immune cells recruitment and fibrosis; IDO1 may be a potential target for the treatment of liver fibrosis." (PMID 33414436, 2021). "Moreover, the expression of IDO1 in the liver of mice with liver fibrosis was increased but was not significantly different from that in the control mice." (PMID 28465467, 2017). "Again, the yield of CD11c+CD80+, CD11c+CD86+cells did not vary between hepatic NPCs harvested from IDO1−/− fibrotic mice, or WT fibrotic mice and knock out of IDO1 did not influence the expression levels of CD80 and CD86 on hepatic CD11c+DCs during liver fibrosis induced by BDL." (PMID 33414436, 2021).
lymphoma (19 papers, 2015 to 2025). A malignant (clonal) proliferation of B- lymphocytes or T- lymphocytes which involves the lymph nodes, bone marrow and/or extranodal sites. "IDO1 inhibitors combined with CD19 CAR-T immunotherapy improved the efficacy of CD19 CAR-T–cell therapy in mouse lymphoma xenograft models." (PMID 36618700, 2022). "It has been shown that intrasplenic injection of lymphoma cells in mice leads to Treg recruitment and that this effect is counteracted by IDO1 inhibition." (PMID 35071240, 2021). "Despite no statistical difference in IDO1 expression levels seen between the groups, all diagnostic and transformed lymphomas exhibited positive expression, indicating its possible role in novel treatment regimens." (PMID 37108483, 2023). "Therefore, in the present study, we aimed to describe IDO1 expression in lymphoma tissue both at FL diagnosis and, as importantly, at transformation." (PMID 37108483, 2023). "IDO-1 inhibitors are also under investigation in clinical trials alone and in combination with other therapies in different advanced malignancies, including lymphomas." (PMID 32260340, 2020).
tuberculosis (19 papers, 2012 to 2024). A chronic, recurrent infection caused by the bacterium Mycobacterium tuberculosis. "Chitinase, Indoleamine 2,3-dioxygenesae-1 (IDO-1) and heme oxygenase-1 (HO-1) are candidate diagnostic biomarkers for tuberculosis (TB)." (PMID 36814914, 2023). "Previous studies have shown that IDO1 is expressed predominantly in macrophages and dendritic cells (DCs) within tuberculosis-infected lungs, with increased enrichment of macrophages." (PMID 39438693, 2024). "Correlation analysis revealed that the expression levels of IDO1 mRNA in the lungs of tuberculosis patients were negatively correlated with the infiltration of CD4+ T and CD8+ T cells." (PMID 39438693, 2024). "In this study, we found that the expression levels of IDO1 in lung tissues from tuberculosis patients were negatively correlated with T-cell infiltration." (PMID 39438693, 2024). "Test characteristics of kynurenine and tryptophan abundance, the K/T ratio, and IDO-1 expression for the diagnosis of pediatric tuberculosis and treatment response." (PMID 35095848, 2021). "In the case of kynurenine, this has been reported to have a significant higher level in blood of tuberculosis patients possibly due to an increased level of the enzyme indoleamine 2,3 dioxygenase 1 (IDO1) that converts tryptophan." (PMID 34233759, 2021). "Elevated levels of IDO-1 mRNA expression were detectable in sputum samples in a cohort of tuberculosis patients." (PMID 22649518, 2012). "Previous studies have shown that the use of IDO1 inhibitors can improve the distribution of T cells within tuberculosis granulomas in macaques, promoting increased infiltration of T cells into granulomas and thereby enhancing the effectiveness of bacterial eradication." (PMID 39438693, 2024). "In light of the high prevalence of patients infected with both HIV and M. tuberculosis our findings indicate that therapeutic targeting of IDO-1 should not increase the risk of exacerbating tuberculosis in HIV patients." (PMID 22649518, 2012). "However, IDO1 expression is also increased in other mycobacterial diseases such as tuberculosis, which might decrease its specificity." (PMID 34695167, 2021). "Therefore, although M. tuberculosis induces robust expression of IDO-1 and activation of tryptophan metabolism, IDO-1-deficiency fails to impact on the immune control and the outcome of the infection in the mouse model of tuberculosis." (PMID 22649518, 2012). "IDO-1 expression in infected mouse lungs has been reported, and elevated IDO-1 expression has recently been correlated with the expression of other inflammatory markers, including C-reactive protein and poor prognosis of tuberculosis patients." (PMID 22649518, 2012). "Recently, the effect of indoleamine 2,3-dioxygenase-1 (IDO) activity in various diseases, including tuberculosis (TB) and human immunodeficiency virus (HIV) disease has generated considerable interest." (PMID 31737575, 2019).